RYR2 (ryanodine receptor 2)
Diseases named in the same sentence as RYR2 in open-access papers (continued):
Sharing a sentence is not in itself a finding about the gene and the disease.
Arrhythmia (continued). "Our findings highlight the importance of atrial subcellular structures, especially RyR2 and LTCC distributions, in the genesis of SCaEs and DADs, which are well-known triggers of cardiac arrhythmias." (PMID 30166973, 2018). "Although RYR2 is not among the canonical genes implicated in classical LQTS, there is growing recognition of its involvement in atypical or overlapping arrhythmia phenotypes." (PMID 40910028, 2025). "Recently, the RyCal S36 corrected Ca2+ leak in human iPSC-derived cardiomyocytes from a patient with CPVT (RyR2-E4076K) by reducing RyR2-mediated Ca2+ spark activity and prohibited arrhythmia but not the progression of heart failure in mice." (PMID 38012000, 2024). "Ex vivo hearts did develop VF in response to isoproterenol but had no arrhythmias in the presence of the RyR2 agonist caffeine." (PMID 37775650, 2023). "RYR2 mutations, including two compound heterozygous missense mutations, were identified in five unrelated BECTS cases with or without arrhythmia." (PMID 33897349, 2021). "Thus, our data further support the link between RyR2 LOF and a new entity of cardiac arrhythmias distinct from CPVT." (PMID 33825858, 2021). "Disruption of the RyR2-FKBP interaction by oxidative stress has also been identified as the mechanism by which palmitoyl-carnitine (PC) promotes RyR2 leakage and, subsequently, cardiac arrhythmia." (PMID 33585462, 2020). "In addition, RyR2 is an important molecular target of oxidative stress in cardiac myocytes, and RyR2 dysfunction could result in mitochondrial abnormalities and increased ROS production, dysmorphology and malfunction, which contributed to the pathogenesis of cardiac arrhythmia." (PMID 31143551, 2019). "Similarly, in inducible, heart tissue-specific RyR2 knockout mice, both in vivo ECG telemetry and in vitro isolated perfused heart, demonstrated bradycardic BI and arrhythmia." (PMID 25755643, 2015). "Among 36 genotype-negative index patients selected for RYR2 screening based on a history of arrhythmia, aborted cardiac arrest and/or syncope and/or a family history of SCD, we identified a disease-causing mutation in 8%." (PMID 23098067, 2012). "However, oxidation‐resistant CaMKII‐MM281/282VV does not protect RyR2‐RS mice from β‐adrenoceptor stimulation‐induced Ca2+ waves or arrhythmias." (PMID 34558218, 2021). "Furthermore, 50% of the RyR2‐RS mice developed VT (6/12), that is, the most severe arrhythmia observed, while no such arrhythmias were observed in WT mice (0/9)." (PMID 34558218, 2021). "However, the role of RyR2 in the pathogenesis of scTdP, characterized by arrhythmias at rest, in the absence of adrenergic stimulation, is less known." (PMID 33664309, 2021). "The role of CaMKII-dependent induced increase in SR Ca2+ leak and ventricular arrhythmias was later confirmed by experiments by Gyorke’s group, which revealed that replacement of Ser2814 site of RyR2 by Ala -a non-phosphorylatable amino acid-prevents ouabain-induced Ca2+ leak and arrhythmias." (PMID 32038301, 2019). "Previous studies have reported modest reductions in RyR2 inhibition but no changes in SK3 channel regulation, while the broad expression of CaM suggests that extra-cardiac manifestations may also occur, as evidenced by distinct neuronal phenotypes of arrhythmia-associated CaM variants in C. elegans." (PMID 41294816, 2025). "Consistent with this, we did not observe any difference in arrhythmia score or incidence of VT between RyR2‐RS/MMVV and RyR2‐RS mice." (PMID 34558218, 2021). "Conversely, the CPVT R2474S RyR2 demonstrated increased FKBP12.6 affinity, while enhanced FKBP12.6 binding did not alter arrhythmias in R4496C mice." (PMID 31028179, 2019). "Moreover, analysis of the arrhythmia subtypes did not reveal any difference between RyR2‐RS/MMVV and RyR2‐RS." (PMID 34558218, 2021).
heart failure (152 papers, 2009 to 2026). Inability of the heart to pump blood at an adequate rate to meet tissue metabolic requirements. "On the other hand, > 50% reductions in RyR2 are more likely associated with heart failure and increased mortality." (PMID 38464671, 2024). "MitoROS contributes to DM-associated ventricular arrhythmic risk and heart failure with preserved ejection fraction (HFpEF) through oxidizing the downstream ryanodine receptor 2 (RyR2) channel and cardiac myosin binding protein C, respectively." (PMID 38889387, 2024). "Calcium handling disturbances including reduced expression levels of the type 2 ryanodine receptor (RYR2) are linked to cardiac dysfunction; here we have created a RYR2 deficient human cardiomyocyte model that mimics some aspects of heart failure." (PMID 39041002, 2024). "Initially, the benzothiazepine derivative JTV519 (K210) was shown to correct SR Ca2+ leak in dog samples with heart failure and decreased human RyR2 activity in recombinant channels harboring missense mutations." (PMID 38012000, 2024). "Expression for proteins responsible for excitation–contraction coupling (Atp2a2/Serca2a, Cav1.2/Cacna1c, Ryr2) was dysregulated in MI animals, consistent with pathological remodeling associated with MI and progression to heart failure." (PMID 37801130, 2023). "In agreement with the mouse data, RyR2 associated-PDE4D levels are reduced in heart failure patients." (PMID 36766777, 2023). "In heart failure patients and failing canine hearts, the Ser2808 was found to be hyperphosphorylated due to the loss of phosphatase activity in the RyR2 complex." (PMID 36766777, 2023). "This interaction is critical to maintaining RyR2 stability as disease-related mutations at these domains unzip RyR2 leading to an unstable open (leaky) state predominantly observed during heart failure." (PMID 34200203, 2021). "Hyperphosphorylation of the RyR2 has been associated with heart failure and treatment with BBs reduces RyR2 phosphorylation and improves Ca2+-handling in these patients." (PMID 34831263, 2021). "Delayed Ca2+ release and reuptake are typical signs of heart failure and have been linked to slowed Ca2+ spark kinetics due to reorganization of RyR2 clusters." (PMID 34558411, 2021). "UhiPSCs from a patient with ventricular septal defects (VSDs) and heart failure (HF) showed the retention of the mutation in the ryanodine receptor type 2 (RyR2), a gene that plays an important role in HF progression." (PMID 31071994, 2019). "Several cardiac pathologies, including myocardial infarction and heart failure, are associated with increased RyR2 activity and diastolic SR Ca leak." (PMID 30574097, 2018). "This is important as leaky RyR2 channels are considered to be the cause of mitochondrial Ca2+ overload and dysfunction in heart failure." (PMID 28630041, 2017). "Although it is undisputed that RyR2 channels contribute directly to the pathology of heart failure, the underlying cause of abnormal RyR2 functioning remains uncertain." (PMID 28630041, 2017). "Aberrant Ca2+ release through the cardiac ryanodine receptor (RyR2), which represents diastolic Ca2+ leak from sarcoplasmic reticulum (SR), is a major cause of heart failure and lethal arrhythmia." (PMID 25614983, 2015). "There has been much controversy over the idea that FKBP12.6 acts as a natural ‘stabiliser’ of RyR2 activity in cardiac cells and that in heart failure there is a lower level of FKBP12.6 associated with RyR2." (PMID 22363773, 2012). "Changes in FKBP12.6 binding to cardiac ryanodine receptors (RyR2) are implicated in mediating disturbances in Ca2+-homeostasis in heart failure but there is controversy over the functional effects of FKBP12.6 on RyR2 channel gating." (PMID 22363773, 2012). "PDE4D deficiency in the ryanodine-receptor complex (RyR2) in mice was also involved in heart failure." (PMID 21151982, 2010).
heart failure (continued). "K201 corrects the defective channel gating in RyR2 and causes a rapid conformational change and increased Ca2+ release in heart failure." (PMID 19442077, 2009). "Marks and coworkers in many studies and perspectives, indict RyR2 and Ca2+ leak as causal of arrhythmias and sensitivities to heart failure." (PMID 19125184, 2009). "Downregulation of RyRs activity has been found in diseases involving loss-of-function mutations (RyR1-related diseases and RyR2 calcium release deficiency syndrome) and reduced expression of RyRs (myopathies, sarcopenia, heart failure, cardiomyopathies, ICU muscle weakness, and others) (13, –15)." (PMID 40512792, 2025). "A malfunctioning RYR2 leads to a leakage of diastolic Ca2+ from the SR, contributing to delayed after-depolarizations which it is believed to be the underlying cause of fatal arrhythmias in heart failure and CPVT." (PMID 40910028, 2025). "Oxidative stress affecting RyR2 destabilizes interdomain interactions within the RyR2 (RyR2 dispersion) which causes calcium leakage from the SR and seems to play a key role in the pathogenesis of heart failure." (PMID 37509534, 2023). "Physiologically, RyR2 is triggered to release Ca2+ from the sarcoplasmic reticulum (SR) which enables cardiac contraction; however, spontaneous Ca2+ leak from RyR2 has been implicated in the pathophysiology of heart failure (HF)." (PMID 37890552, 2023). "Indeed, studies using a mouse model have shown that a RYR2 mutation with a locus in the CaM-binding site (reducing receptor inactivation) causes cardiac hypertrophy, heart failure, and early sudden death." (PMID 37958665, 2023). "Recent evidence suggests that in heart failure SR Ca2+ leak causes mitochondrial calcium overload that triggers mitochondrial dysfunction and the production of free radicals, which in turn modulates RyR2 function." (PMID 28630041, 2017). "Irregular RyR2 activity is linked to various forms of heart failure, but the underlying molecular mechanisms that cause altered RyR2 channel function remain unclear." (PMID 28630041, 2017). "Although RyR2 mutations that impair CaM regulation in cardiac pathologies have not yet been identified, our studies should help to understand the role of RyR2 regulation by CaM and CaMKII in cardiac hypertrophy and heart failure in humans." (PMID 25093823, 2014). "Additionally, mice expressing the RyR2 S2814A mutation are protected from the development of heart failure in response to pressure overload consistent with a critical role for CaMKII-mediated RyR2 phosphorylation." (PMID 24575042, 2014). "In addition, RYR2 initiates cardiac excitation-contraction coupling by Ca2+-induced Ca2+ release and some amino acid mutations in RYR2 have been linked to heart failure in humans." (PMID 25078401, 2014). "A leaky RyR2 could possibly be linked to all major drawbacks of heart failure: impaired systolic force generation, compromised passive diastolic relaxation and a disposition for arrhythmias." (PMID 22932727, 2013). "The dissociation of FKBP12.6 from RyR2 has been linked with heart failure and arrhythmia generation and it has been proposed that the ensuing dysfunctional RyR2 channel behaviour contributes to the defective Ca2+ homeostasis that is characteristic of heart failure." (PMID 22363773, 2012). "In fact, several mutations in RyR1 and RyR2 proteins cause decreased affinity between RyRs and calstabins, leading to abnormal calcium cycling, a major hallmark of several cardiac phenotypes, including heart failure." (PMID 22236651, 2012). "In this study, we observed CaMKII-mediated RyR2 phosphorylation (Ser-2448) and protein kinase A-mediated RyR2 phosphorylation (Ser-2808) in the heart of PG-LPS-treated mice, which might be associated with SR Ca2 + leakage via the RyR2 channel and heart failure." (PMID 40179080, 2025). "Moreover, pathological Ca2+ channel remodeling and heart failure progression are linked to RYR2." (PMID 37109540, 2023).
heart failure (continued). "Importantly, RyR2 hyperoxidation has been associated with reduced cardiac function and/or increased arrhythmic potential in various cardiac diseases including heart failure, infarct, diabetic cardiomyopathy, age-related cardiac dysfunction, and even inherited cardiac arrhythmia syndromes." (PMID 37138037, 2023). "The mechanism for CRU breakup remains to be established, but could include loss of accessory proteins tethering RyR2 clusters together, or simply CRU failing to keep up with cellular remodeling (e.g., hypertrophy in the case of heart failure and possibly RyR2 mutations)." (PMID 35892340, 2022). "Thus, inhibition of CaMKII dependent‐RyR2 hyperphosphorylation by chronic exercise training may be a key mechanism underlying the suppression of ventricular arrhythmias in heart failure after MI." (PMID 30806037, 2019). "Despite this controversy on the causal role of RyR2-mediated sarcoplasmic reticulum Ca(2+)-leak for AF progression, several other studies point to important roles of the RyR2-complex in AF-related pathophysiologies such as aging, oxidative stress, heart failure and impaired glucose tolerance." (PMID 27857207, 2016). "For example, excessive RyR2-mediated calcium leak and CaMKII overactivation are involved in both ventricular ectopy and mechanical dysfunction in heart failure." (PMID 40843724, 2025). "If unmitigated, this progression culminates in heart failure over time, RyR2-mediated pathological Ca2+ leakage is a significant precipitant of delayed afterdepolarizations." (PMID 40943170, 2025). "Meanwhile, previous reports show that PDE4D3 also binds to RyR2, and global deletion of PDE4D leads to calcium leakage through RyR2 and heart failure in ageing mice." (PMID 39662482, 2025). "In heart failure, hyperphosphorylation of RyR2 at Ser2808 mediated by PKA, resulting from β-adrenergic stimulation, impaired FKBP12.6 binding to the RyR2 channels and the final leak of Ca2+ from SR." (PMID 39820183, 2025). "Just as orphaned (i.e., misaligned) RyR2 clusters are known to produce arrhythmogenic Ca2+ release in ventricular myocytes in heart failure, TAT depletion has been detected in atrial myocytes derived from sheep with AF." (PMID 39804820, 2025). "New therapeutic strategies for heart failure aimed at stabilizing RyR2 channels to fix the leak are now being tested." (PMID 41439978, 2025). "This phosphorylation-dependent reduction in Mg2+ inhibition is particularly evident in heart failure, where RyR2 hyperphosphorylation correlates with decreased channel sensitivity to cytoplasmic Mg2+." (PMID 40862759, 2025). "In a mouse model of heart failure, they demonstrated that PS improved cardiac function and rhythmicity by stabilizing ryanodine receptor 2 (RyR2)-mediated calcium release from the sarcoplasmic reticulum and inhibiting STIM1-mediated calcium entry." (PMID 40970182, 2025). "The restoration of efficient calcium handling, particularly through preserved SERCA2a function and reduced RyR2-mediated calcium leak, directly addresses the diastolic dysfunction that characterizes many heart failure phenotypes, especially HFpEF." (PMID 41154632, 2025). "Previous evidence shows that changes in compartmentalised cAMP–PKA signalling at RyR2 and myofilaments exert important pathological effects in heart failure induced by stenosis and aortic insufficiency." (PMID 39662482, 2025). "In human heart failure, the association between PDE4D3 and RyR2 is diminished, contributing to hyperphosphorylated and ‘leaky’ RyR2 channels." (PMID 40136709, 2025). "Recent high-resolution imaging studies have revealed that RyR2 clusters lose their structural integrity in heart failure, with important functional consequences for Ca handling." (PMID 41278880, 2025). "Previous studies have demonstrated that the reverse mode of NCX plays a crucial role in activating RyR2 in mouse ventricular myocytes and directly regulates the action potential of heart failure cells." (PMID 38911325, 2024).
heart failure (continued). "Pathologically increased SR Ca2+ leak through RyR2 dysfunction combined with decreased SERCA2a function represents hallmarks in acquired forms of cardiac diseases including heart failure." (PMID 38012000, 2024). "Impairments in the regulation of Ca2+ cycling proteins, including the ryanodine receptor 2 (RyR2) and the sarcoplasmic/endoplasmic reticulum Ca2+ ATPase 2a (SERCA2a)/phospholamban (PLN) complex, are implicated in heart failure." (PMID 39273430, 2024). "In light of our numerous prior investigations of the potential therapeutic role of THs in heart failure, we focused this study on the effects of T3 on Jph2 localization with RyR2 clusters and organization within the dyad using a TH-deficient disease model." (PMID 39365674, 2024). "Conditional cardiomyocyte specific knock-out (KO) of Ryr2 leads to rapid onset of heart failure and sudden death." (PMID 39041002, 2024). "(C) The percent carbonyl content/mg of protein was lower in dantrolene (DS)-treated heart failure animals, showing reversal of RyR2 oxidation profile with DS therapy in HF animals (p<0.005, N≥4)." (PMID 38078905, 2023). "Oxidizing agents also increase RyR2-mediated Ca2+ leak in permeabilized isolated ventricular myocytes, further supporting the role of redox regulation of RyR2 in heart failure." (PMID 37891912, 2023). "In particular, increased expression/activity of NCX and elevated PKA-dependent phosphorylation of RyR2 are hallmarks of heart failure." (PMID 37372947, 2023). "These potentially life-saving effects of RyR2 inhibition warrant further investigation, such as clinical studies of repurposing dantrolene as a potential new therapy for heart failure and/or SCD." (PMID 38078905, 2023). "Increased phosphorylation of RyR2 at S2814 (by CaMKII) in heart failure appears to be the dominant mechanism rendering RyR2 leaky with detrimental effects on contractility and arrhythmogenesis." (PMID 37372947, 2023). "We previously showed that beta-blockers reduced PKA-phosphorylation of RyR2 in human and canine models of heart failure and in CPVT hiPSC-CMs." (PMID 37740238, 2023). "The mechanistic role of RyR2 hyperphosphorylation in heart failure and arrhythmia remains controversial." (PMID 36766777, 2023). "In conclusion, hyperphosphorylation of RyR2 leads to increased diastolic Ca2+ leak in heart failure, but the effect of CaMKII is more specific on RyR2, and CaMKII phosphorylation is more important than PKA." (PMID 35457253, 2022). "RyR2 phosphorylation occurs during beta adrenergic stimulation, which can occur during normal physiology, such as exercise, or during diseases such as heart failure." (PMID 36358926, 2022). "The spontaneous release of Ca2+ by RyR2 (Ca2+ leak) has been shown to contribute to arrhythmogenesis, including in heart failure (HF) and atrial fibrillation (AF)." (PMID 33718369, 2021). "Clustering properties of RyR2 have been suggested to alter the activity of the channel, with remodeling of RyR2 clusters identified in pre-clinical models of AF and heart failure." (PMID 33718369, 2021). "Strong oxidative stress responses occur after burns and include the activation of RyR2 and leakage of calcium from the SR in cardiomyocytes, which leads to heart failure." (PMID 34639137, 2021). "S107, a specific and oral 1,4-benzothiazepine derivative shown to stabilize FKBP12.6/RyR2 complex, can reduce RyR2-mediated SR Ca2+ leak and thereby prevent heart failure progression." (PMID 32669538, 2020). "The therapeutic potential of targeting RyR2-mediated SR Ca2+ leak for treating heart failure and arrhythmia is also very well documented." (PMID 32019969, 2020). "RyR2 hyperphosphorylation is known to contribute on arrhythmogenesis in the context of heart failure." (PMID 32868781, 2020). "All of these, in addition to heart failure and arrhythmia, have been suggested to originate, at least in part, through RyR2 phosphorylation and a decrease in its affinity for the immunophilin FKBP12.6 (calstabin 2)." (PMID 31916935, 2020).